CLEC7A (C-type lectin domain containing 7A)
Diseases named in the same sentence as CLEC7A in open-access papers (continued):
Sharing a sentence is not in itself a finding about the gene and the disease.
tumor (114 papers, 2012 to 2026). "CLEC7A, which is highly expressed in M2-like tumor-associated macrophages, is linked to galectin 9, thus leading to tolerogenic macrophage programming and adaptive immunosuppression that contribute to tumor exacerbation." (PMID 35480896, 2022). "Overexpression of CD74, CLEC7A, and IFI30 in macrophages further enhanced M2 polarization, which was associated with increased tumor-promoting functions, including enhanced invasion and reduced apoptosis in GBM cells." (PMID 41892299, 2026). "By KEGG gene enrichment analysis, we found that immune related genes such as antibody production, lymphocyte activation, NK cell-mediated cytotoxicity, and antigen presentation were upregulated in tumor tissues of Clec7a−/− mice compared to that of WT mice." (PMID 36932082, 2023). "CRC-associated cells contained lymphocytes, NK, myeloid-derived cells, mast cells, fibroblasts, epithelial, endothelial, and tumor cells, and CLEC7A was mainly expressed in myeloid-derived cells." (PMID 36932082, 2023). "Conversely, activation of CLEC7A can exert effective anti-tumor immunity by enhancing the expression of interleukin-33 and interleukin-9 in dendritic cells and by inducing differentiation of naive CD4+T cells into T-helper 9 cells." (PMID 35480896, 2022). "Dectin-1 (CLEC7A), a C-type lectin receptor, exhibits dual roles in cancer immunity, acting as either an immunosuppressive or immunostimulatory agent depending on the tumor context and ligand availability." (PMID 41163402, 2025). "When AOM-3DSS-induced colonic polyp-derived MHC-II−Gr1+ cells were co-cultured with splenic CD4+ T cells, T cell proliferation was suppressed by these tumor-infiltrating Gr1+ cells from WT mice, while Gr1+ cells from Clec7a−/− mouse polyps suppressed T cell population only weakly." (PMID 36932082, 2023). "By scRNA-seq analysis, we found a group of DCs, which we named tumor-associated DC (TADC) because this DC subset uniquely expresses tumor-associated genes such as Pclaf, Spc24 and Top2a, highly expressed Il22ra2 in Clec7a−/− mice but not in WT mice." (PMID 36932082, 2023). "Interestingly, certain tumour entities, which show increased Annexin expression correlated with immune infiltration also show a correlation of high Annexin receptor (Dectin-1/CLEC7A) expression with worse prognosis." (PMID 36123610, 2022). "The altered expression of Clec7a in lung tissue of mice treated with T. stromaticum conidia allows us to speculate that dectin-1 may be involved in the increased tumor uptake and increased number of visible nodules in our model through mechanisms that are still not clear." (PMID 32547964, 2020). "It is shown that CLEC7A, VCAN, and KYNU were significantly upregulated in monocytes, BIRC3 and SOD1 were mainly distributed in T cells, CCL20 was highly expressed in tumor cells, and CD69 was highly expressed in B cells." (PMID 35480896, 2022). "The 48 h coculture initiates a pro-tumor phenotype skewing of MΦ, indicated by downregulation of IL1B, IL12, CCL18, CD80, as well as CD163, and upregulation of CLEC7A (dectin-1), CD86, CD206, and HLA-DR." (PMID 30850595, 2019). "The expression of Clec7a was elevated in polyps compared with non-polyp tissues, reflecting the expansion of tumor-infiltrating MDSCs in which Dectin-1 was highly expressed." (PMID 36932082, 2023). "Consistent with this view, genes in the activated clusters also matched transcriptome modules described in activated microglia in neurodegeneration models (such as Itgax and Clec7a), but not in tumor or acute inflammation models." (PMID 36624100, 2023). "TCGA-STAD and GEO datasets analysis indicated higher CLEC7A mRNA expression in tumour tissues compared with adjacent normal tissues." (PMID 37422529, 2023). "In a mouse model of PDA, Clec7a deletion significantly reduced the infiltration of PDA with F4/80+, CD206+ and Arg1+ TAMs, as well as upregulated MHCII, TNF-α and iNOS expression in tumor." (PMID 36686729, 2022).
tumor (continued). "In the non-responder tumor the 'CLEC7A/inflammasome pathway' is the most prominent dysregulated pathway potentially available for therapeutic intervention." (PMID 28594404, 2017). "Whereas the responder tumor engages PD-1 checkpoint inhibition, the non-responder tumor has already upregulated the 'CLEC7A/inflammasome pathway'." (PMID 28594404, 2017). "Interestingly, we found that in PD-L1+ tumours (PD-L1 combined positive score (CPS) ≥1), patients belonging to CLEC7A/CD68 high subgroup held more non-responders compared with CLEC7A/CD68 low subgroup, indicating that Dectin-1+ TAMs might be involved in resistance to anti-PD-1 therapy." (PMID 37422529, 2023).
cancer (41 papers, 2012 to 2025). A tumor composed of atypical neoplastic, often pleomorphic cells that invade other tissues. "As a pattern-recognition receptor, Clec7a has been found to recognize a broad range of microbial pathogens, including fungi and bacteria, which can cause autoimmune disorders and cancer." (PMID 36503542, 2022). "Besides, accumulated evidence has suggested that CLEC7A had dual effects on cancer, namely, inhibiting and promoting cancer." (PMID 35480896, 2022).
neurodegenerative disease (9 papers, 2019 to 2025). A disorder of the central nervous system characterized by gradual and progressive loss of neural tissue and neurologic function. "This phenotype partially overlaps with microglial signatures described in neuroinflammation and neurodegenerative diseases and includes genes such as Itgax, Clec7a and genes associated with APC functions, commonly thought of as inflammatory." (PMID 38195627, 2024). "Several of the most highly induced genes from the microglia gene sets (Clec7a, Cybb, Itgax, and Csf1) are specific markers of the “primed” microglia, a status associated with aging and neurodegenerative diseases." (PMID 31549781, 2019). "Interestingly, we also detected reductions in disease-associated microglia (DAM)/microglial neurodegenerative disease (MGnD) genes such as Cst7, Clec7a, and Spp1, suggesting that microglia adopted a dampened DAM/MGnD state despite no changes in IBA1+ microglia staining." (PMID 36922879, 2023). "Notably, CLEC7A is also highly ranked for LATE+AD vs. pure AD and LATE vs. pure AD, which was implicated in neurodegenerative diseases in prior studies." (PMID 34492068, 2021). "CLEC7A (FC = 2.02, p = 0.02) is a disease-associated microglia gene which has been shown to increase after TBI in mice, in a mouse model of AD, and in aged microglia associated with neurodegenerative disease." (PMID 33964983, 2021). "Interestingly, genes associated with the recently characterized neurodegenerative disease-associated phenotype (DAM microglia), such as Clec7a, Csf1, Cd74, Cxcl10 and Cybb, were downregulated in 5xFAD/Gal3KO mice compared to 5xFAD mice." (PMID 31006066, 2019). "Interestingly, the role of Clec7a in neurodegenerative diseases appears context dependent." (PMID 40243488, 2025).
neurological diseases (7 papers, 2021 to 2025). "DAM genes Clec7a, Itgax and Cst7 are associated with innate immune responses in the setting of neurological diseases." (PMID 36419137, 2022). "Given the growing number of literature and the emerging significance of Clec7a in neurological disease, it presents a compelling target for further investigation." (PMID 39088351, 2024). "Additionally, other up-regulated DEGs, like C-type lectin domain family 7 member A (Clec7a) and lysozyme 2 (Lyz2), have been reported to have detrimental effects on other neurological disorders." (PMID 39905541, 2025). "Growing evidence shows that C-Type Lectin Domain Containing 7A (Clec7a) may be involved into neuroinflammatory injury of various neurological diseases." (PMID 36503542, 2022).
hematologic disease (5 papers, 2012 to 2022). "Three studies have demonstrated that CLEC7A (Dectin-1) or CD209 (DC-SIGN) variants are associated with the development of IA in patients with hematologic malignancies, and this is further supported by a study finding decreased CLEC7A expression in hematologic malignancy patients with IA." (PMID 32185141, 2020).
inflammation (5 papers, 2012 to 2024). Aberrant reaction of the microcirculation characterized by movement of fluid and leukocytes from the blood into extravascular tissues. "An intriguing finding in this study was that HDM-associated airway inflammation is accompanied by an increased expression of Dectin-1/Clec7a, implying that signalling downstream of this receptor may contribute to the inflammatory response in this setting." (PMID 37153590, 2023).
infectious disease (4 papers, 2018 to 2023). A disorder directly resulting from the presence and activity of a microbial, viral, or parasitic agent in humans. "Very little is known about this microglial phenotype, therefore we explored the expression of Clec7a, one marker of disease-associated (DAM) microglia together with other markers at the crosstalk between infectious diseases and AD." (PMID 37341831, 2023). "Finally, new restorative markers for other infectious diseases might be found by exploring nine functionally identified CLEC7A SNPs." (PMID 29616193, 2018).
bacterial infections (3 papers, 2009 to 2020). "CLEC7A, a member of C-type lectin receptors, is produced by myeloid cells to sense pathogens and bacterial infections and could activate immune cells in diarrhea-predominant irritable bowel syndrome." (PMID 33392192, 2020).
kidney disease (1 paper, 2025). "SYK is activated downstream of DAMP-sensing C-type lectin receptors such as CLEC4E (Mincle, Clec4e) and CLEC7A (Dectin-1, Clec7a) that have been implicated in kidney disease." (PMID 40857403, 2025).
CLEC7A also shares sentences with these, for which no sentence is quoted: candidiasis (13 papers); Arthritis (12); Allergy (11); asthma (10); fungal keratitis (10); inflammatory bowel disease (9); Insulin resistance (9); liver fibrosis (7); pancreatic ductal adenocarcinoma (7); atherosclerosis (6); Immunodeficiency (6); clear cell renal cell carcinoma (5); pneumonia (5); Sepsis (5); acute myeloid leukemia (4); corneal infection (4); COVID-19 (4); Crohn disease (4); cryptococcal infection (4); diabetes (4); helminth infection (4); keratitis (4); lung adenocarcinoma (4); chromoblastomycosis (3); Cognitive impairment (3); myocardial ischemia (3); pulmonary sarcoidosis (3); renal failure (3); rheumatoid arthritis (3); sporotrichosis (3).
A further 126 diseases each share a sentence with CLEC7A in 2 papers or fewer.